CABYR (calcium binding tyrosine phosphorylation regulated)
Description:
May function as a regulator of both motility- and head-associated functions such as capacitation and the acrosome reaction. Isoform 1 binds calcium in vitro. Isoform 2 and isoform 6 probably bind calcium. Isoform 3 and isoform 5 do not bind calcium in vitro. Isoform 4 probably does not bind calcium.
Synonyms: CT88; FSP-2; CBP86; FSP2; CABYRa; CABYRc; CABYRc/d; CABYRe
Tractability: Antibody: its Gene Ontology location is reachable by antibodies, with medium confidence.
Gene: Protein-coding gene on chromosome 18 (24,138,987 to 24,161,603, forward strand). Ensembl gene ENSG00000154040.
Subcellular location: Cytoplasm, cytoskeleton; Cell projection, cilium, flagellum; Nucleus (Isoform 1); Cytoplasm; Nucleus (Isoform 3); Nucleus (Isoform 5)
Subcellular location (Human Protein Atlas): Cytosol; Nucleoplasm; Principal piece
Gene Ontology:
Molecular function: calcium ion binding; SH3 domain binding; protein domain specific binding
Biological process: epithelial cilium movement involved in extracellular fluid movement; sperm capacitation
Cellular component: cytoplasm; cytosol; motile cilium; nucleoplasm; nucleus; sperm fibrous sheath; sperm principal piece; cytoskeleton; extracellular region; sperm end piece
Genetic constraint (gnomAD): Loss-of-function variants: 26 observed, 30.7 expected, observed/expected ratio (o/e) 0.85, 90% interval 0.62 to 1.17. The upper end of that interval is the gene's LOEUF score, 1.17, which puts it in group 5 of 6, group 1 being the genes least tolerant of losing a copy. Missense variants: 405 observed, 457.06 expected, observed/expected ratio (o/e) 0.89, 90% interval 0.82 to 0.96. Synonymous variants: 139 observed, 164.06 expected, observed/expected ratio (o/e) 0.85, 90% interval 0.74 to 0.98.
Homologues: Orthologues: dog CABYR (76% identical), mouse Cabyr (75% identical), guinea pig CABYR (73% identical), chimpanzee CABYR (48% identical), macaque CABYR (47% identical), pig CABYR (38% identical), rat Cabyr (32% identical).
Diseases named in the same sentence as CABYR in open-access papers:
CABYR is named in the same sentence as 14 diseases in open-access papers, as found by Europe PMC text mining. Sharing a sentence is not in itself a finding about the gene and the disease. The quoted sentences say what the papers report.
lung carcinoma (6 papers, 2016 to 2023). "To explore the underlying mechanism through which CABYR-a/b inhibits TRAIL-induced apoptosis in lung cancer cells, we examined the expression of death receptors DR4 and DR5." (PMID 26843620, 2016). "By performing real-time PCR to determine expression levels of CABYR a/b and c in the tissues of lung cancer patients, they were able to find expression in 36% and 42% of lungs cancer tissues, respectively." (PMID 33747357, 2021). "Subsequently, to confirm that CABYR-a/b was required for TRAIL-induced apoptosis in lung cancer cells, we selected CABYR-a and performed a rescue experiment in CABYR-silenced cells and the corresponding control cells." (PMID 26843620, 2016). "Taken together, our results demonstrate that depletion of CABYR-a/b sensitizes lung cancer cells to TRAIL-induced apoptosis through YAP/p73-mediated DR5 upregulation." (PMID 26843620, 2016). "Our previous study revealed that knockdown of CABYR-a/b increases the chemosensitivity of lung cancer cells through inactivation of Akt." (PMID 26843620, 2016). "In the present study, we found that silencing of CABYR-a/b sensitized lung cancer cells to TRAIL-induced apoptosis both in vitro and/or in vivo." (PMID 26843620, 2016). "Stable knockdown CABYR-a/b was established in H460 and A549 lung cancer cell lines, which express higher levels of endogenous CABYR-a/b compared to other lung cancer cell lines tested." (PMID 26843620, 2016). "To examine how CABYR-a/b inhibits DR5 expression in lung cancer cells, we examined the expression of YAP and p73." (PMID 26843620, 2016). "Our previous study established that depletion of CABYR-a/b inhibited the proliferation and increased the chemosensitivity of lung cancer cells in vitro and in vivo via inhibition of the Akt pathway." (PMID 26843620, 2016). "In our previous study, we verified CABYR as a novel cancer testis antigen in lung cancer." (PMID 26843620, 2016). "However, few studies have evaluated the biological functions of CABYR in cancer cells, with the exception of studies performed in liver and lung cancer cells." (PMID 26843620, 2016). "In addition to lung cancer and brain tumors, CABYR was also shown to be aberrantly expressed in liver cancer and esophageal cancer." (PMID 26843620, 2016). "Taken together, we demonstrate for the first time that depletion of CABYR-a/b up-regulates DR5 expression and sensitizes TRAIL-induced apoptosis through the YAP/p73 transcriptional axis in lung cancer cells." (PMID 26843620, 2016). "Here, we demonstrated that depletion of CABYR-a/b significantly increased DR5 expression and sensitized lung cancer cells to TRAIL-induced apoptosis in vitro and/or in vivo." (PMID 26843620, 2016). "The present study provides the first evidence that depletion of CABYR-a/b decreases YAP S127 phosphorylation and upregulates the expression of p73 and DR5, thus increasing TRAIL-induced apoptosis in lung cancer cells." (PMID 26843620, 2016). "a calcium-binding tyrosine phosphorylation–regulated protein that was identified as a novel cancer testis antigen in lung cancer, a negative correlation existed between the expression level of CABYR-a/b and TRAIL-induced apoptosis in lung cancer cells." (PMID 28121627, 2017). "The results demonstrated that hsa_circ_0008705 (circ-CABYR) and hsa_circ_0025583 (circ-SLCO1B7) consistently displayed changes in expression in response to AR manipulation, suggesting a potential regulatory role of AR in modulating the expression of these circRNAs in lung cancer cells." (PMID 37564195, 2023).
lung carcinoma (continued). "However, it has been reported that CABYR-a/b increases tumour necrosis factor receptor superfamily, member 10b (DR5) expression and sensitizes lung cancer cells to the tumour necrosis factor-related apoptosis-inducing Ligand (TRAIL)-induced apoptosis in vitro and in vivo." (PMID 35574342, 2022). "Collectively, our results strongly suggest a negative correlation between the expression level of CABYR-a/b and TRAIL-induced apoptosis in lung cancer cells." (PMID 26843620, 2016).
asthenospermia (2 papers, 2019 to 2021). "CABYR and ROPN1 mRNA were significantly downregulated in asthenozoospermia patients' samples and a positive correlation was confirmed between the expression of the two genes, indicating that the co-expression of CABYR and ROPN1 was a prerequisite for normal sperm motility and flagellar function." (PMID 33746583, 2021).
colon cancer (2 papers, 2017 to 2021). "As mentioned, IHC was also carried out to assess for the presence of CABYR proteins in colon cancer." (PMID 33747357, 2021). "As regards mRNA, notable CABYR a/b and c expression was noted in tissue samples of colon cancer and normal testis/placenta." (PMID 33747357, 2021). "It was noted that CABYR protein was, in fact, frequently expressed in many of the colon cancer samples that were analyzed." (PMID 33747357, 2021). "Our findings displayed that LSD1-target genes, namely, CABYR and CDH1 might be potential LSD1-target genes in colon cancer cells, and revealed the underlying mechanisms of invasion and metastasis in colon cancer." (PMID 28121627, 2017). "LSD1- overexpression mediated the downregulation of CABYR and CDH1expression through decreasing the mono- and dimethylation of H3K4 at LSD1-target gene promoter in colon cancer cells." (PMID 28121627, 2017). "In this study, we assessed these possible LSD1-targets, including CABYR and CDH1, which could be the newly identified target genes by comparing the effects of LSD1 in the two colon cancer cells." (PMID 28121627, 2017).
varicocele (2 papers, 2015 to 2024). A condition characterized by the dilated tortuous veins of the spermatic cord with a marked left-sided predominance. "The reduced expression of CABYR in varicocele patients is suggestive of its involvement in poor sperm motility seen in these patients, as low CABYR would entail impaired energy supply to the flagella and consequently spermatozoa movement." (PMID 25890347, 2015). "Additionally, proteins such as enkurin (ENKUR), semenogelin-1 and -2 (SEMG1/2), sperm adhesion molecule 1 (SPAM1), and CABYR serve as indicators of reduced semen quality in bilateral varicocele patients." (PMID 39685846, 2024). "CABYR, SEMG-1 preproprotein, RSPH1and SPA17 were underexpressed in the unilateral varicocele group." (PMID 25890347, 2015). "Notable proteins include calcium-binding tyrosine phosphorylation-regulated protein (CABYR), A-kinase anchor proteins (AKAP), APOA1, semenogelin-1 (SEMG1), and sperm surface protein Sp17 (SPA17), which have been highlighted as potential biomarkers for unilateral varicocele." (PMID 39685846, 2024).
colorectal cancer (1 paper, 2021). A primary or metastatic malignant neoplasm that affects the colon or rectum. "The aim of this study is to evaluate the CABYR isoforms: a/b and c mRNA expression in colorectal cancer (CRC) and to determine if these proteins hold promise as vaccine targets." (PMID 33747357, 2021). "In conclusion, this study assessed colorectal cancer specimens for CABYR a/b and c expression." (PMID 33747357, 2021).
colorectal tumor (1 paper, 2021). "In the present study, expression levels of CABYR a/b and c are compared in 47 paired colorectal tumor and normal colonic tissue specimens." (PMID 33747357, 2021). "Additionally, CABYR c is highly expressed in hepatocellular carcinoma tissues and may play an oncogenic role in hepatocarcinogenesis, Thus far, the expression of CABYR in colorectal tumors has not been previously studied." (PMID 33747357, 2021).
large bowel adenocarcinomas (1 paper, 2021). "The purpose of this study was to determine CABYR expression in human CRC and to determine if this protein holds promise as a possible vaccine target for large bowel adenocarcinomas." (PMID 33747357, 2021).
meningioma (1 paper, 2023). A generally slow growing tumor attached to the dura mater. "Regarding HLA class II, 26 antigens were exclusively identified in the peptidome of meningiomas, with MAGEA10, MUTYH, and CABYR being the most frequent (6–15% positive tumors)." (PMID 37368072, 2023).
non-small cell lung carcinoma (1 paper, 2022). A group of at least three distinct histological types of lung cancer, including non-small cell squamous cell carcinoma, adenocarcinoma, and large cell carcinoma. "The knockdown of CABYR chemosensitivity through inactivating AKT pathway in non-small cell lung cancer cells." (PMID 36299585, 2022).
cancer (8 papers, 2015 to 2024). A tumor composed of atypical neoplastic, often pleomorphic cells that invade other tissues. "Both XAGE1B and CABYR are tumor-specific antigens of the Cancer Testis Antigens (CTA), which have attracted research attention as potential mediators of cancer cell recognition." (PMID 35804987, 2022). "Ideally, reasonable numbers of specimens for each cancer stage would be assessed; the need for Stage 4 tumors is especially important to determine if CABYR expression, in general and for the individual isoforms, correlates with disease stage." (PMID 33747357, 2021). "We selected those genes with functions known to be associated with cancer of which there were 12—SNVs: NOTCH2, PIK3CG, IL2RB, BAI3, FREM2 and RERE; indels: UTRN, CDHR3, NCOA5, CABYR, HOTAIR and FOLH1." (PMID 26017033, 2015). "Furthermore, other CRRGs, such as PPA2, DGAT1, and CABYR, have been shown to be involved in the oncogenic effects of other cancers and to affect patient prognosis, despite the fact that related studies are uncommon in BC." (PMID 36685904, 2022). "In addition, FSIP1 can bind to and activate cancer/testis antigen proteins (including CABYR, SPA17, AKAP3, AKAP4, and ROPN1) in the fibrous sheath in tumor cells, in turn promoting cancer progression." (PMID 28086239, 2017). "Therefore, the full biological functions of CABYR in cancer cells have yet to be elucidated." (PMID 26843620, 2016). "We could use siRNA specifically targeting CABYR-a/b as a small molecule drug to treat cancers." (PMID 26843620, 2016). "We further focused on four key genes (CABYR, FOXF2, TLE4, and CDH1 ) related to proliferation, apoptosis, tumorigenesis, invasion and metastasis of cancer cells." (PMID 28121627, 2017). "Subsequently, CABYR-a/b-silenced and control cells were treated with an agonistic DR5 monoclonal antibody (AD5-10), which has been reported to specifically bind to DR5 and induce cancer cell apoptosis." (PMID 26843620, 2016). "Upon discovery of this information, it was thought that CABYR might not be a cancer testis antigen." (PMID 33747357, 2021). "Cancer cell lines M1, A549, SNU539, and H226 were tested with mAbs SB2, 3A4 (anti-CABYR, negative control), and AY13 (anti-EGFR, positive control)." (PMID 38485187, 2024).
tumor (6 papers, 2016 to 2024). "Both expression ratios over one and expression levels over 0.1% of testis was noted for CABYR a/b in 23.4% of tumor samples and for CABYR c in 25.5% of samples." (PMID 33747357, 2021). "The data of this study suggests a larger and more diverse group of tumors (Stage I–IV) needs to be assessed to determine if CABYR expression correlates with T, N, or final tumor stage." (PMID 33747357, 2021). "A relative expression ratio of malignant to normal tissues over 1 was noted in 70% of paired samples for CABYR a/b and in 72% of paired tumor/normal tissue sets for CABYR c." (PMID 33747357, 2021). "All 47 samples of tumor and normal tissues (18 male, 29 female) were analyzed for CABYR a/b and c expression via quantitative PCR." (PMID 33747357, 2021). "In this study, tumor expression of both CABYR a/b and CABYR c was determined by quantitative PCR following RT-PCR." (PMID 33747357, 2021). "Non-significant increases in CABYR a/b expression levels were noted in Stage 2 (0.86 ± 1.1) and Stage 3 (1.11 ± 2.1) tumor samples; a similar trend was noted regarding CABYR C expression in Stage 2 (0.93 ± 0.85) and Stage 3 (2.47 ± 7.3) tumors." (PMID 33747357, 2021). "Analysis of CABYR protein expressions by immunohistochemistry in tumor and normal colon tissues was also performed." (PMID 33747357, 2021). "In addition, an increase in CABYR expression was observed in tumor tissues; however, the increase was not statistically significant." (PMID 38694506, 2024). "Presently, because of the relatively small number of samples studied it is not possible to state whether CABYR expression correlates with tumor stage." (PMID 33747357, 2021).
CABYR also shares sentences with these, for which no sentence is quoted: brain tumours (1 paper); colonic adenocarcinoma (1); testicular embryonic carcinoma (1).